NF1 (neurofibromin 1)
Diseases named in the same sentence as NF1 in open-access papers (continued):
Sharing a sentence is not in itself a finding about the gene and the disease.
RASopathies (continued). "We next turned our attention to whether the transcriptomic dataset could provide the basis for tumourigenesis in classical NF1 but not in 3bp deletion NF1, as we had already shown that CALM melanocytes exhibited biallelic loss similar to that observed in tumours arising within RASopathies." (PMID 39355740, 2024). "These children may not be affected by NF1 but instead by Legius syndrome or less frequently by another RASopathy such as Noonan syndrome with multiple lentigines (formerly known as LEOPARD syndrome, MIM#151100) or Constitutive mismatch repair deficiency (CMMRD)." (PMID 34928431, 2022). "If the clinical phenotype is not typical, either multi-gene panels (that include NF1, SPRED1 genes, or rasopathy multigene panel) or comprehensive genomic testing (as exome sequencing or genome sequencing) may be considered." (PMID 39860457, 2025). "Finally, this study focused exclusively on NF1 and NSSD, the two most common RASopathies, and does not address psychiatric outcomes in other syndromes within the RAS-MAPK pathway, such as Costello syndrome or cardiofaciocutaneous (CFC) syndrome." (PMID 40725498, 2025).
cutaneous melanoma (90 papers, 2015 to 2026). A primary melanoma arising from atypical melanocytes in the skin. "The NF1 tumor suppressor gene plays a role in regulating growth in neural crest-derived cells, including melanocytes, and is mutated in some cutaneous melanomas." (PMID 41001300, 2025). "The K81Q mutation was the only RASA2 mutation present in the TCGA-UVM dataset, so its co-occurrence with NF1 copy-number loss is quite interesting, given the previously observed co-occurrence of RASA2 and NF1 mutations in cutaneous melanomas." (PMID 39804140, 2025). "Mucosal melanomas have a mutational profile characterized by KIT as the most frequent mutations (20–25% of cases), followed by BRAF and NRAS mutations (whose frequency is lower than that observed in cutaneous melanomas) and NF1 mutations." (PMID 39727691, 2024). "Somatic NF1 mutations have been reported in 12% to 30% of cutaneous melanoma and 45% to 90% of desmoplastic melanoma." (PMID 39687068, 2024). "The most frequent mutations in MM have been in SF3B1 (27%), KIT (18%) and NF1 (17%), a different pattern from cutaneous melanomas." (PMID 38275835, 2024). "Like in skin melanomas, NF1 mutations can co-exist with either NRAS or BRAF mutations in CMs, albeit infrequently." (PMID 37761808, 2023). "NF1-inactivating mutations are found in acral, mucosal, desmoplastic, and UV-associated skin melanomas." (PMID 37345107, 2023). "The rate of NF1 mutations is comparable to that of cutaneous melanoma (~14%); however, BRAF/NRAS mutations rates are remarkably lower, and KIT mutations are observed in at least 13% of cases." (PMID 38201222, 2023). "It is caused by mutations in the NF1 gene resulting in loss-of-function, which is also the case in cutaneous melanoma." (PMID 35234863, 2022). "MAPK signaling is overactive in the majority of CMs, driven by activating mutations in BRAF (~50%) or NRAS (~25%), or loss of function mutations in NF1 (~15%) (Genomic Classification of Cutaneous Melanoma, 2015)." (PMID 35513054, 2022). "In ultraviolet-shielded melanoma, mutations of BRAF, NRAS or NF1 are less frequent compared to cutaneous melanoma, but the existence of other cancer driver gene mutations are detected." (PMID 35688842, 2022). "In cutaneous melanoma TERT promoter mutations commonly co-occur (80-90%) with NF1, BRAF or NRAS mutations, and TERT promoter mutations are also found in 15-60% of BRAF/NRAS/NF1 WT cutaneous melanoma background." (PMID 35494035, 2022). "NF1 mutation (16.0%) of mucosal melanoma was similar to that in western population, but higher than that of Chinese cutaneous melanoma." (PMID 35688842, 2022). "the NF1 subtype characterized by the presence of mutation on NF1 gene and accounting for ~14% of cutaneous melanomas; iv." (PMID 34123788, 2021). "NF-1 has been described as the third most common mutated TSG seen within those who develop cutaneous melanoma, and once more, loss of NF-1 leads to increased signaling within the MAPK and PI3K pathways due to hyperactivation of the NRAS protein." (PMID 34155457, 2021). "Following BRAF and NRAS, NF1 is the third gene most commonly mutated in cutaneous melanoma (in about 17% of the cases) and frequently co-occurs with mutations in the RASA2 gene." (PMID 33003469, 2020). "Mutations in the tumor suppressor NF1 are observed in approximately 14% of cutaneous melanoma, of which 63% are characterized by a loss-of-function." (PMID 32517051, 2020). "NF1 mutations are associated with sunlight exposure also in cutaneous melanoma and are more frequent in the desmoplastic subtype." (PMID 31683701, 2019). "It has been demonstrated that cutaneous melanomas with NF1 mutations harbor a higher mutational load." (PMID 31683701, 2019). "This is similar to the situation in cutaneous melanoma where the co-occurrence of NF1 with BRAF, RAS and other mutations is well recognised." (PMID 29559732, 2018). "Recently, loss of function mutations in NF1 have been described in a high percentage of cutaneous melanoma." (PMID 28938534, 2017).
cutaneous melanoma (continued). "In addition, NF1 is the third most common mutation in cutaneous melanomas, and it is associated with tumors arising on highly sun-exposed skin." (PMID 37373134, 2023). "NF1 mutation was reported as a major subgroup of cutaneous melanoma by TCGA." (PMID 37831226, 2023). "Moreover, desmoplastic melanoma, an aggressive scarring variant typical of old people that constitutes 4% of all skin melanoma, demonstrates NF1 alterations in up to 55% of cases." (PMID 37627552, 2023). "However, genetic evidence argues these tumors mostly originate from cutaneous sites, as they demonstrate a similar distribution of BRAF, NRAS and NF1 mutations to cutaneous melanoma." (PMID 35565222, 2022). "In addition to NF1 associated MPNSTs, role of NF1 mutations has also been elucidated in other cancer types such as cutaneous melanoma." (PMID 29212209, 2017). "Like in skin melanomas, NF1 mutations appear to occur more frequently in CMs associated with UV signature (typical UV-related C > T or CC > TT nucleotide changes) and higher mutational load, suggesting a potential benefit from immunotherapy in patients with NF1-mutated tumors." (PMID 37761808, 2023). "Thus, NF1 mutations have been reported in 13–17% of cutaneous melanomas overall." (PMID 34331013, 2021). "The genetic abnormalities commonly associated with these two subtypes of cutaneous melanoma are neurofibromin 1 (NF1), NRAS, BRAF non-V600E mutations, or KIT in CSID, while non-CSID is associated with BRAF V600E mutations, suggesting that the non-CSID might originate from nevi." (PMID 33256089, 2020). "Conversely, in CoM, the mutational spectrum overlaps with cutaneous melanoma, with frequent alterations in BRAF, NRAS, NF1, and KIT, offering actionable targets for personalised treatment." (PMID 41751395, 2026). "In this context, The Cancer Genome Atlas (TCGA) project classifies cutaneous melanoma into four major genomic subtypes based on driver mutations: BRAF-mutant, RAS-mutant, NF1-mutant, and triple wild-type." (PMID 41465101, 2025). "NF1 mutations are present in 5% of BRAF-, 13% of NRAS-, and 50% of RASA2-mutant cutaneous melanomas." (PMID 39804140, 2025). "GNAQ and GNA11 mutations are prevalent in primary CNS melanoma but differ from cutaneous melanoma (CM), in which BRAF, NRAS, KIT, and NF-1 mutations are more common." (PMID 41536409, 2025). "The reported frequencies of mutations in cutaneous melanoma are 37–60% in BRAF, 13–25% in NRAS, 12% in NF1, 6–7% in MAP2K1, and 2–8% in KIT." (PMID 41295253, 2025). "Examining the distribution of DEL and INV sizes within cutaneous melanomas revealed that the majority of smaller SV events in this histology were in NF1- and (N)RAS-mutant tumors." (PMID 38758740, 2024). "In cutaneous melanomas, NF1-mutant tumors were enriched for deletion SVs, and had chromothripsis events at nearly twice the rate compared with the other genomic subtypes." (PMID 38758740, 2024). "Mutations that are noted in mucosal melanoma include neurofibromin 1 (NF1), KIT, and splicing factor 3b subunit 1 (SF3B1); NRAS and BRAF mutations occur at far lower rates than traditional cutaneous melanoma." (PMID 39001457, 2024). "According to TCGA data for cutaneous melanoma, activations of RAF, RAS or loss of NF1, the three most frequently mutated genes, can subsequently activate the MAPK signaling pathway." (PMID 37277447, 2023). "Blocking ERK activation rescued IFNγ-mediated apoptosis in 17 of 23 (~ 74%) cell lines representing BRAF, NRAS, NF1 mutant, and triple wild type subtypes of cutaneous melanoma." (PMID 37803324, 2023). "The most commonly mutated driver genes in cutaneous melanomas are the proto-oncogene B-Raf (BRAF) (~45–50%), Ras GTPase (RAS) (~30%), and neurofibromin 1 (NF1) (~10–15%)." (PMID 36901857, 2023). "The major subtype is cutaneous melanoma (CM), which usually accompanies the BRAF(v-raf murine sarcoma viral oncogene homolog B1), RAS (Rat sarcoma virus), NF1(Neurofibromatosis 1), and TWT(triple wild-type) mutations." (PMID 35837089, 2022).
cutaneous melanoma (continued). "The Cancer Genome Atlas (TCGA) research defined molecular subtypes of cutaneous melanoma on the basis of the presence of specific “driver” gene (BRAF, RAS, and NF1) mutations." (PMID 35688842, 2022). "CM shares similarities with both cutaneous melanoma and mucosal melanoma, including their infiltrative nature, their lymphatic and hematogenous spread and the presence of BRAF, NRAS, NF1 and Kit mutations." (PMID 34830847, 2021). "Cutaneous melanomas can be classified into four main genetic subtypes: BRAF mutated, RAS mutated, NF1 mutated, and triple-wildtype." (PMID 35008286, 2021). "The most frequent mutations in mucosal melanoma were in SF3B1 (27%), KIT (18%), and NF1 (17%), a pattern that is distinct from cutaneous melanomas." (PMID 33724703, 2021). "Commonly to cutaneous melanoma, mucosal mutations shows alterations in SF3B1, KIT, and NF1 and less frequently mutations in BRAF and NRAS." (PMID 33918490, 2021). "Mutations in KIT, NF1 and SF3B1 genes are more frequently seen in mucosal melanomas, while alterations to NRAS and BRAF genes are more common in cutaneous melanomas." (PMID 34209084, 2021). "Like cutaneous melanomas, it has been proposed to classify CMs according to their mutational status, resulting in groups of BRAF-mutated, NRAS-mutated, NF1-mutated and triple-wild type (WT) melanomas." (PMID 34830847, 2021). "Mutations that upregulate the pathway, including BRAF (B rapidly accelerated fibrosarcoma kinase), RAS (rat sarcoma virus small GTPase), and NF1 (neurofibromin 1), are found in more than 80% of cutaneous melanomas." (PMID 35008286, 2021). "For instance, The Cancer Genome Atlas (TCGA) defined three genomic subtypes of cutaneous melanoma based on the mutation status of BRAF, NRAS, NF1, and a fourth subgroup termed triple wild-type." (PMID 32517051, 2020). "We divide cutaneous melanoma into four subtypes (BRAF-mutant, NF1-deficient, NRAS-mutant and triple wild-type)." (PMID 33585219, 2020). "AM also has different oncogenic drivers from cutaneous melanoma, including inconstant KIT mutation rates (3–29%), CCND1 and CDK4 amplification, and deletion or mutations in different genes, such as CDK2NA, PTEN, NF1, and hTERT." (PMID 33344255, 2020). "We validated previous reports that the commonly known mutations in cutaneous melanoma, including BRAF, NRAS, NF1, GNAQ and GNA11, were rarely mutated in mucosal melanomas." (PMID 30847022, 2019). "Cutaneous melanoma can be divided into molecular subgroups (BRAF mutated, NRAS mutated, NF1 mutated, triple wild-type) and show the typical ultra violet (UV) signature (C > T transition)." (PMID 31500314, 2019). "Approximately 90% of human cutaneous melanomas are driven in part by BRAF, RAS, NF1, and KIT mutations that confer constitutive mitogenic signaling through the MAPK pathway." (PMID 30188888, 2018). "The majority of human cutaneous melanomas are driven in part by constitutive activation of the MAPK pathway through mutation of genes such as BRAF, NRAS, NF1, KIT, GNAQ, and GNA11, often in a mutually exclusive pattern." (PMID 30188888, 2018). "This case illustrates a primary cutaneous melanoma presenting with a solitary pulmonary metastasis in a patient with NF1." (PMID 25893129, 2015). "For example, nearly two thirds of NF1-mutant cutaneous melanomas carry a second MAPK gene hit." (PMID 39804140, 2025). "However, it is worth briefly mentioning some important driver mutations, including mutations of the BRAF oncogene, that are present in 60% of all cutaneous melanomas, mutation in the oncogene NRAS and the tumour suppressor gene neurofibromatosis 1 (NF1)." (PMID 39727823, 2024).
cutaneous melanoma (continued). "Hotspot mutations predominantly in the V600 codon of BRAF and the Q61 codon of NRAS, as well as loss-of-function events in NF1, led to a cascade of perturbations causing upregulation of the MAPK pathway, the most deregulated signalling pathway in cutaneous melanoma." (PMID 38201222, 2023). "Although targeted therapy has evolved in the last years and significantly improved the prognosis of patients with cutaneous melanoma, its use in vulvar and vaginal melanomas is still limited by the different mutagenic profiles involving fewer BRAF mutations and more c-KIT, NF1 and SF3B1 mutations." (PMID 34209084, 2021). "For instance, the majority of cutaneous melanoma harbor mutations of B-Raf proto-oncogene, serine/threonine kinase (BRAF), NRAS proto-oncogene, GTPase (NRAS) and neurofibromin 1 (NF1) as well as loss of cyclin dependent kinase inhibitor 2A (CDKN2A) encoding P16NK4a." (PMID 34830903, 2021). "AM has different oncogenic drivers from the cutaneous melanoma, including fewer BRAF mutations (10–23%), inconstant KIT mutation rates (3–29%), CCND1 and CDK4 amplification, and deletion or mutations in different genes, such as CDK2NA, PTEN, NF1, and hTERT." (PMID 33344255, 2020). "Notably, dysfunction mutations of NF1 induce BRAF inhibitor resistance by activating RAS and its downstreams including both MAPK and PI3K/AKT/mTOR pathways in cutaneous melanoma." (PMID 32333246, 2020). "For example, for thymomas the CIMLR subtypes perform better at predicting survival than histological classification, while the CIMLR subtypes of cutaneous melanoma are much better at predicting survival than classification based on BRAF, RAS, and NF1 mutations." (PMID 30367051, 2018). "A significant proportion of cutaneous melanomas harbor recurring (hot spot) mutations in BRAF (approximately 50%), RAS (approximately 20%), and/or NF1 (approximately 25%) genes, and these mutations can be associated with constitutive activation of the MAPK signaling pathway." (PMID 29385676, 2018). "A relevant role for NF1 mutations in cutaneous melanomas lacking conventional (i.e. BRAF or NRAS) activating mutations has been already highlighted by other studies." (PMID 28380455, 2017). "The association of UV-exposure with NF1 mutations observed in cutaneous melanoma is not to be expected in mucosal melanoma." (PMID 28380455, 2017). "Unlike skin melanomas and CMs, however, uveal melanomas do not typically harbor NF1 mutations." (PMID 37761808, 2023). "For example, whereas mutations in the classic TSG NF1 interact with CNA loss in most cancer types (62.5%), the driver mutations in BRAF only interact with CNA gain in one of the four cancer types in which it is significantly mutated (skin cutaneous melanoma; SKCM)." (PMID 34862370, 2021). "Data published in the Cancer Genome Atlas (TCGA) Network classify cutaneous melanomas into four genetic subgroups on the basis of the most frequently mutated genes involved in the mitogen-activated protein kinase (MAPK) pathway: BRAF, RAS (N-H-K), NF1, and triple wild-type (WT) melanomas." (PMID 33003469, 2020). "Cutaneous melanoma (CM) is genetically heterogeneous and classified into four major subtypes—BRAF-mutant, RAS-mutant, NF1-mutant, and triple wildtype (BRAF/RAS/NF1 wildtype)—with the latter often harboring KIT or GNAQ/GNA11 mutations." (PMID 40565936, 2025). "According to the Cancer Genome Atlas (TCGA) classification, cutaneous melanoma comprises four main subtypes: BRAF-mutant (~50%), NRAS-mutant (~20%), NF1-mutant (~10–15%) and triple negative/wild-type (~10–15%)." (PMID 41465101, 2025).